SHARPIN (SHANK associated RH domain interactor)
Description:
Component of the LUBAC complex which conjugates linear polyubiquitin chains in a head-to-tail manner to substrates and plays a key role in NF-kappa-B activation and regulation of inflammation. LUBAC conjugates linear polyubiquitin to IKBKG and RIPK1 and is involved in activation of the canonical NF-kappa-B and the JNK signaling pathways. Linear ubiquitination mediated by the LUBAC complex interferes with TNF-induced cell death and thereby prevents inflammation. LUBAC is recruited to the TNF-R1 signaling complex (TNF-RSC) following polyubiquitination of TNF-RSC components by BIRC2 and/or BIRC3 and to conjugate linear polyubiquitin to IKBKG and possibly other components contributing to the stability of the complex. The LUBAC complex is also involved in innate immunity by conjugating linear polyubiquitin chains at the surface of bacteria invading the cytosol to form the ubiquitin coat surrounding bacteria. LUBAC is not able to initiate formation of the bacterial ubiquitin coat, and can only promote formation of linear polyubiquitins on pre-existing ubiquitin. The bacterial ubiquitin coat acts as an 'eat-me' signal for xenophagy and promotes NF-kappa-B activation. Together with OTULIN, the LUBAC complex regulates the canonical Wnt signaling during angiogenesis.
Synonyms: SIPL1; DKFZP434N1923; AIFID
Tractability: Antibody: the Human Protein Atlas places it where antibodies can reach. PROTAC: ubiquitination databases record sites on it; a small molecule that binds it is known.
Gene: Protein-coding gene on chromosome 8 (144,097,513 to 144,108,124, reverse strand). Ensembl gene ENSG00000179526.
Subcellular location: Cytoplasm, cytosol; Synapse
Subcellular location (Human Protein Atlas): Plasma membrane; Cytosol; Golgi apparatus
Pathways (Reactome):
Signal Transduction: Regulation of TNFR1 signaling; TNFR1-induced NF-kappa-B signaling pathway; TNFR1-induced proapoptotic signaling
Neuronal System: Neurexins and neuroligins
Gene Ontology:
Molecular function: polyubiquitin modification-dependent protein binding; protein binding; ubiquitin binding; ubiquitin-protein transferase activity; protein-macromolecule adaptor activity
Biological process: defense response to bacterium; positive regulation of canonical NF-kappaB signal transduction; protein linear polyubiquitination; regulation of CD40 signaling pathway; regulation of tumor necrosis factor-mediated signaling pathway; negative regulation of inflammatory response; proteasome-mediated ubiquitin-dependent protein catabolic process; protein ubiquitination
Cellular component: cytosol; LUBAC complex; synapse
Genetic constraint (gnomAD): Loss-of-function variants: 24 observed, 37.43 expected, observed/expected ratio (o/e) 0.64, 90% interval 0.46 to 0.9. The synonymous counts are far from expectation, so gnomAD's model fits this gene poorly and the ratio says little. Missense variants: 543 observed, 481.29 expected, observed/expected ratio (o/e) 1.13, 90% interval 1.05 to 1.21. Synonymous variants: 270 observed, 207.5 expected, observed/expected ratio (o/e) 1.3, 90% interval 1.18 to 1.44.
Homologues: Orthologues: chimpanzee SHARPIN (99% identical), macaque SHARPIN (94% identical), pig SHARPIN (78% identical), guinea pig SHARPIN (76% identical), mouse Sharpin (73% identical), rat Sharpin (70% identical), dog SHARPIN (66% identical), zebrafish shrprbck1r (37% identical), zebrafish sharpin (36% identical), tropical clawed frog rbck1 (30% identical), zebrafish rbck1 (17% identical). Paralogues in human: RBCK1 (25% identical), RNF216 (16% identical).
Diseases named in the same sentence as SHARPIN in open-access papers:
SHARPIN is named in the same sentence as 86 diseases in open-access papers, as found by Europe PMC text mining. Sharing a sentence is not in itself a finding about the gene and the disease. The quoted sentences say what the papers report.
dermatitis (16 papers, 2012 to 2024). An inflammatory process affecting the skin. "Spontaneous mutations giving rise to dermatitis and internal organ inflammation in two laboratory mouse strains helped lead to the identification of SHANK-associated RH domain-interacting protein (SHARPIN)." (PMID 37569318, 2023). "Introduction of E3-defective HOIL-1L mutants augmented linear ubiquitination, protecting cells against Salmonella infection and curing dermatitis caused by reduction in LUBAC levels due to loss of SHARPIN." (PMID 34685685, 2021). "In contrast to HOIL-1- and HOIP-deficiency, mice deficient in SHARPIN (Sharpincpdm/cpdm) are viable but present with severe multi-organ inflammation and progressive dermatitis with alopecia that develops from 3–4 weeks of age." (PMID 33924766, 2021). "The expression of CCL24 was more consistently and strongly increased compared with CCL11 in the skin of mutant mice suggesting a more important role for CCL24 in the dermatitis of SHARPIN-deficient mice." (PMID 32687504, 2020). "Consistent with active RIP1 contributing to inflammation in the skin, Cpdm mice that are deficient in SHARPIN develop severe skin inflammation unless they also express inactive RIP1 D138N." (PMID 31101885, 2020). "In summary, we report CerAS(d18:1/24:0)2OH, CerAS(d18:1/16:0)2OH, CerNS(d18:1/16:0), cerotic acid, 16-hydroxy palmitic acid, and docosahexaenoic acid (DHA) as highly discriminative lipids in the dermatitis of SHARPIN-deficient mice." (PMID 29698466, 2018). "A role for IL33 in the dermatitis in SHARPIN-deficient mice is supported by the attenuation of inflammation in Sharpincpdm mice in which IL1RAP was deleted." (PMID 24465642, 2014). "Keratinocyte-specific deletion of caspase 8 and the FAS-associated death domain (FADD) adaptor protein result in increased necroptosis of keratinocytes and cutaneous inflammation that is strikingly similar to the dermatitis in SHARPIN-deficient mice." (PMID 24465642, 2014). "Chronic proliferative dermatitis mutation (cpdm) mice lack SHARPIN and develop dermatitis." (PMID 35547743, 2022). "Interestingly, while RIP3 loss delays the development of dermatitis in SHARPIN deficient mice, MLKL loss does not affect the development of dermatitis." (PMID 32671059, 2020). "The dermatitis in SHARPIN-deficient mice is associated with apoptosis of keratinocytes." (PMID 32687504, 2020). "The dermatitis in SHARPIN‐deficient cpdm mice is caused by cell or tissue intrinsic defects leading to TNF‐induced cell death of keratinocytes and it is not mediated by immune cells as allogeneic BM or splenocyte transplantations fail to transfer the disease to WT mice." (PMID 30804083, 2019). "Identification and rapid monitoring of these lipids represent a tool to assess therapeutic outcomes in SHARPIN-deficient mice and other mouse models of dermatitis and may have diagnostic utility in atopic dermatitis." (PMID 29698466, 2018). "Mice deficient in SHARPIN (Sharpincpdm mice), a member of linear ubiquitin chain assembly complex (LUBAC), develop severe dermatitis associated with systemic inflammation." (PMID 27892465, 2016). "Because SHARPIN has distinct roles in different cell types, we examined earlier time points to evaluate the link between dermatitis and systemic inflammation." (PMID 27892465, 2016). "Our results altogether demonstrate distinct roles of SHARPIN in initiating systemic inflammation and dermatitis." (PMID 27892465, 2016). "SHARPIN-deficient mouse embryonic fibroblast (MEF) were sensitized to TNFα-induced apoptosis and cell death was implicated as a factor in the dermatitis of cpdm mice." (PMID 22348129, 2012). "A HOIL-1L NZF mutant lacking the ubiquitin-binding activity exacerbates the skin inflammation phenotype of SHARPIN-deficient mice (cpdm mice)." (PMID 39528476, 2024).
dermatitis (continued). "Taken together, it could be proposed that SHARPIN has distinct roles in the initiation of immune cell dysregulation and dermatitis and that skin intrinsic defects drive dermatitis in Sharpincdpm mice." (PMID 27892465, 2016). "Given that SHARPIN indeed inhibits integrin activity in mouse epidermis, we hypothesized that the increased Itgb1 activity might contribute to the Sharpincpdm/cpdm dermatitis phenotype." (PMID 29040328, 2017). "Once mice lack SHARPIN or HOIP, they can lead to severe dermatitis or embryonic lethality, respectively." (PMID 35547743, 2022). "However, SHARPIN-deficient immune cells are not sufficient to establish dermatitis when transferred to WT recipients, as the Sharpincpdm ≫ WT chimeras do not develop any signs of dermatitis, even up to 12 months of age8." (PMID 27892465, 2016). "TNFR1 activity is directly required for the skin inflammation in cpdm mice as SHARPIN-null animals that were also null for Tnfrsf1a did not develop cutaneous inflammation." (PMID 37569318, 2023). "Our data indicate that, while TNF-induced cell death triggers the chronic inflammation and proliferative dermatitis, absence of SHARPIN-dependent integrin inhibition exacerbates the epidermal hyperproliferation in Sharpincpdm/cpdm mice." (PMID 29040328, 2017). "Furthermore, mutant mice lacking SHARPIN develop severe autoinflammatory diseases (severe dermatitis and system-wide organ inflammation) and immunodeficiency due to destabilization of the two remaining LUBAC subunits." (PMID 34434197, 2021). "Thus, the immune cell dysregulation and dermatitis observed in Sharpincpdm mice is independent of each other and due to distinct roles of SHARPIN in immune cells and non-hematopoietic cells." (PMID 27892465, 2016). "To address whether SHARPIN truly acts as an integrin inhibitor in vivo, we made use of the Tnfr1-/-Sharpincpdm/cpdm double knockout mice, in which the skin thickening, chronic inflammation and dermatitis, typical to Sharpincpdm/cpdm mice, are absent." (PMID 29040328, 2017). "However, as Sharpincpdm/cpdm mice suffer from chronic proliferative dermatitis, it has remained unclear whether increased integrin activity in the Sharpincpdm/cpdm epidermis is due to lack of SHARPIN or merely a side effect of the dermatitis." (PMID 29040328, 2017). "Likewise increased keratinocyte apoptosis may contribute to inflammation, and is also tied to NFKB, as supported by the increased sensitivity of SHARPIN-deficient cells to TNF-induced necroptosis and the lack of dermatitis in TNF-deficient Sharpincpdm mice." (PMID 24465642, 2014). "This suggests that keratinocyte damage in the absence of SHARPIN may lead to release of TSLP and IL33, which initiate the dermatitis through the activation of ILC2 and basophils." (PMID 32687504, 2020). "Since the dermatitis and inflammatory phenotype were shown to be TNF dependent, and because the only TNF signaling output that was aberrantly increased in the absence of SHARPIN was cell death, we previously proposed TNF/TNFR1-mediated cell death to be causative of the cpdm phenotype." (PMID 25443632, 2014).
breast carcinoma (11 papers, 2015 to 2023). "In addition to its involvement in breast cancer progression, SHARPIN is also strongly associated with metastasis in breast cancer." (PMID 35547743, 2022). "However, our results for SHARPIN do not support any association between SHARPIN gene expression and breast cancer progression, where SHARPIN expression significantly decrease in high stages." (PMID 29763465, 2018). "At present, several gene expression analyses targeting tumor biopsy tissue are underway, and the human SHARPIN gene is upregulated in tumorigenesis in various human cancers such as breast cancer, esophageal cancer and renal cell carcinoma." (PMID 35547743, 2022). "Molecular biological studies had shown that SHARPIN can promote breast cancer development by regulating the ubiquitination of ERα proteins, during which SHARPIN is not involved in regulating gene expression." (PMID 35547743, 2022). "Recent studies have shown that SHARPIN is frequently upregulated in multiple human cancer types, including ovarian, prostate, and breast cancers, hepatocellular carcinoma and melanoma." (PMID 34178683, 2021). "This study identifies the first time, the ubiquitin binding protein SHARPIN as a modulator of ERα signaling in human breast cancer cells." (PMID 29100376, 2017). "To approach the function of SHARPIN in breast cancer cells in an unbiased way, we analyzed changes in previously generated global gene expression profiles following SHARPIN depletion in MCF-7 breast cancer cells (Assessing number: GSE77261)." (PMID 29100376, 2017). "SHARPIN is highly expressed in human breast cancer and correlates with ERα protein level by immunohistochemistry." (PMID 29100376, 2017). "Here, we identify SHARPIN to control ERα ubiquitination and stability and thereby the transcriptional regulation of ERα target genes and breast cancer cell proliferation." (PMID 29100376, 2017). "To investigate the role of SHARPIN in cell proliferation, we utilize ERα-positive breast cancer cell MCF7 as a model." (PMID 29100376, 2017). "A γRV shuttle vector approach identified previously known (WWTR1, RIN1) and also novel (SHARPIN) breast cancer metastasis genes." (PMID 27792127, 2016). "Four genes WWTR1, RIN1, MAF1 and SHARPIN were identified having significant expression levels in breast cancer patients by meta-analysis." (PMID 27792127, 2016). "A γRV shuttle vector insertional mutagenesis screen identified SHARPIN as a novel breast cancer metastasis driver gene in vivo." (PMID 27792127, 2016). "A recent study found that SHARPIN stabilizes ERα and promotes breast cancer cell proliferation." (PMID 38017534, 2023). "Follow-up of patients and evaluation of the expression of RBCK1, RNF31 and SHARPIN with tumor recurrence and overall survival of patients may further shed lights on the prognostic role of this complex on breast cancer." (PMID 29763465, 2018). "In the study, we examine the role of SHARPIN in ERα positive breast cancer cells." (PMID 29100376, 2017). "SHARPIN depletion significantly decreases estrogen stimulated cell proliferation in breast cancer cells, which effect could be further rescued by ERα overexpression." (PMID 29100376, 2017). "SHARPIN depletion significantly decreases ERα protein level, ERα target genes expression and estrogen response element activity in breast cancer cells, while SHARPIN overexpression could reverse these effects." (PMID 29100376, 2017). "SHARPIN expression level correlates with poor prognosis in ERα positive breast cancer patients." (PMID 29100376, 2017). "Together, our findings propose a novel ERα modulation mechanism in supporting breast cancer cell growth, in which SHARPIN could be one suitable target for development of novel therapy for ERα positive breast cancer." (PMID 29100376, 2017).
breast carcinoma (continued). "SHARPIN knockdown in breast cancer cells significantly reduced clonogenicity in vitro and metastasis in vivo providing independent validation that SHARPIN affects breast cancer metastasis." (PMID 27792127, 2016). "SHARPIN was involved in prostate cancer and breast cancer progression but its role in breast cancer metastasis was still unknown, while MAF1 had no known involvement in cancer progression." (PMID 27792127, 2016). "Meta-analysis of OncomineTM breast cancer patient microarray data showed a significant increase in SHARPIN expression in patients and SHARPIN expression affected metastasis free survival in breast cancer patients after adjuvant chemotherapy treatment as identified by SurvExpress." (PMID 27792127, 2016). "Collectively, our findings indicate that up-regulated mRNA expression of RNF31, RBCK1 and SHARPIN could potentially be diagnostic biomarkers of breast cancer and RNF31 might be a drug target for ERalpha-negative breast cancers." (PMID 29763465, 2018). "In all, SHARPIN could be a promising therapeutic strategy for breast cancer treatment." (PMID 29100376, 2017). "Importantly, SHARPIN depletion could rescue tamoxifen sensitivity, hamper estrogen-dependent cell proliferation and decrease ERα signaling in multiple breast cancer cell lines." (PMID 29100376, 2017). "In an in vivo screen with breast cancer cells mutagenized with a replication-incompetent gammaretroviral vector, SHARPIN and RIN1 were described as novel breast cancer metastasis genes." (PMID 36497409, 2022). "While ERalpha has already been well documented to play an important role in the etiology and progression of breast cancer, RBCK1, RNF31 and SHARPIN has recently emerged as potential new players in tumorigenesis." (PMID 29763465, 2018). "A survey of LUBAC component expression found that the mRNA expression levels of all three subunits, HOIP, HOIL-1, and SHARPIN, are higher in breast cancer samples compared to adjacent non-tumor tissue." (PMID 38017534, 2023).
melanoma (10 papers, 2020 to 2024). A malignant, usually aggressive tumor composed of atypical, neoplastic melanocytes. "We again inoculated the opposing flanks of mice with WT or SHARPIN-deficient B16F1 melanomas cells, and 10 days later, when both tumors were detectable and of similar size, we initiated therapy with anti-PD1 mAb or isotype control." (PMID 34752416, 2021). "Interestingly, as many as 814 genes were common to both clusters, therefore one single gene was exclusively mutated in melanoma cluster 0 patients: SHARPIN, a regulator of melanomagenesis already described to promote melanoma proliferation, metastasis, and invasion." (PMID 39602407, 2024). "Applying this procedure to melanoma patients has unveiled SHARPIN, a gene known to be involved in melanomagenesis and disease progression, as being critical for the worse survival of patients, a result that confirms the performance of the tool." (PMID 39602407, 2024). "SHARPIN promotes melanoma development via p38 and JNK/c-Jun pathways by upregulating Rap1 expression." (PMID 38017534, 2023). "A recent study found a linear ubiquitin-independent role for SHARPIN in melanoma." (PMID 38017534, 2023). "By contrast, higher expression of SHARPIN correlates with worse survival of melanoma." (PMID 38017534, 2023). "Previous studies demonstrated that SHARPIN, which was highly expressed in melanoma tissues, could mediate the activity of its downstream pathways (p38, JNK/c- Jun), thereby promoting the proliferation and metastasis of cancer cells." (PMID 36829196, 2023). "Similar to its role in melanoma, SHARPIN interacts with PRMT5 in lung cancer cells." (PMID 38017534, 2023). "PET imaging in vivo was evaluated in wild-type (wt) and SHARPIN-deficient mice (Sharpincpdm, where cpdm 5 designates chronic proliferative dermatitis in mice) with and without melanoma tumor allografts." (PMID 33810198, 2021). "SHARPIN can be involved in the regulation of PRMT5 activity, in turn increasing the proportion of transcriptional activity of PAX3 and MITF involved in melanoma growth." (PMID 35547743, 2022).